SCN1B (sodium voltage-gated channel beta subunit 1)
Diseases named in the same sentence as SCN1B in open-access papers (continued):
Sharing a sentence is not in itself a finding about the gene and the disease.
Brugada syndrome (16 papers, 2013 to 2025). A genetically heterogeneous condition characterized by complete or incomplete right bundle branch block accompanied by ST elevation in leads V1-V3. "No abnormal cardiac findngs occurred, despite the theoretical risk of arrhythmias associated with Brugada syndrome in SCN1B-related phenotypes." (PMID 36291443, 2022). "SCN1B variants also cause cardiac arrhythmogenic conditions such as Brugada syndrome, and herein, we will focus on the neurodevelopmental and epileptic manifestations of SCN1B pathogenic variants." (PMID 36291443, 2022). "The SCN1B (p.Thr189Met) variant was detected in sudden unexplained nocturnal death syndrome and atrial fibrillation cases." (PMID 35663268, 2022). "Variants in SCN1B, the gene encoding the Nav-β1 and -β1B subunits, are linked to atrial and ventricular arrhythmias, e.g., Brugada syndrome, as well as to the early infantile epileptic encephalopathy Dravet syndrome, all of which put patients at risk for sudden death." (PMID 29740331, 2018). "Finally two SCN1B mutations, V138I and T189M, have been related to sudden unexplained nocturnal death syndrome (SUNDS), a disorder whose electrocardiogram (ECG) characteristics and clinical phenotype are very similar to BrS." (PMID 26042039, 2015). "Pathogenic SCN1B variants have previously been associated with generalized epilepsy with febrile seizures plus, Dravet syndrome, early infantile epileptic encephalopathy, inherited arrhythmia disorders such as Brugada syndrome and various other cardiac abnormalities." (PMID 36291443, 2022). "In another family, quad WES analysis identified a paternally inherited heterozygous missense variant of unknown significance in SCN1B, the gene for Brugada syndrome 5 (MIM 612838), and compound heterozygous changes in POLR1C, segregating in two affected siblings." (PMID 28327206, 2017). "Inherited monoallelic SCN1B variants are linked to genetic epilepsy with febrile seizures plus (GEFS+) and cardiac disorders such as Brugada syndrome and atrial fibrillation (AF), which are also associated with sudden death." (PMID 40763036, 2025). "Other genes, such as SCN1B, SCN2B, SCN3B, and GPD1L, contribute to reduced INa and Brugada syndrome, with various clinical phenotypes associated with these mutations." (PMID 39583597, 2024). "SCN1B variants are linked to DEE52 as well as to cardiac disease, including Brugada Syndrome 5 (BrS5, OMIM 612838) and Atrial Fibrillation Familial 13 (OMIM 615377), although there is evidence to suggest that SCN1B may not be a monogenic cause of BrS." (PMID 40763036, 2025). "SCN1B variants are linked to human cardiac disease, including Brugada syndrome and atrial fibrillation, although recent work suggests that SCN1B may not be a monogenic cause of Brugada syndrome." (PMID 33411695, 2021).
Dravet syndrome (15 papers, 2015 to 2025). "Homozygous SCN1B/β1 pathogenic variants have been later identified in DEE patients that were initially included in the Dravet syndrome spectrum." (PMID 37654020, 2024). "Biallelic pathogenic variants in SCN1B, encoding β1, are linked to developmental and epileptic encephalopathy 52, with clinical features overlapping Dravet syndrome." (PMID 38425576, 2023). "Fenfluramine, and later cannabidiol was added on compassionate basis as it does not have an FDA approval for use in patients less than 1 year of age and in Dravet syndrome associated with the SCN1B genotype–phenotype." (PMID 36291443, 2022). "Patients with biallelic SCN1B variants have been reported in the literature with clinical manifestations consistent with or sharing features of Dravet Syndrome (DS), a developmental and epileptic encephalopathy." (PMID 36291443, 2022). "The patient phenotype is more compatible with early infantile developmental and epileptic encephalopathy (DEE) than with typical Dravet syndrome (DS), as previously diagnosed for other patients with homozygous SCN1B variants." (PMID 31709768, 2019). "Therefore, researchers looked for other genetic etiologies, such as an association between Dravet Syndrome and mutations in the SCN1B gene." (PMID 36291443, 2022). "We identified an unrelated biallelic SCN1B-c.265C>T patient with a clinically more severe phenotype than Dravet syndrome." (PMID 38425576, 2023). "Scn1b-null mice that lack both b1 and b1B exhibit spontaneous seizures, ataxia, poor weight gain, and premature death around post-natal day 19, modeling Dravet Syndrome, a DEE." (PMID 36291443, 2022). "Biallelic variants in SCN1B are associated with DEE, ranging from severe early onset DEE to a phenotype milder than but resembling Dravet syndrome." (PMID 36291443, 2022). "Seven cases were diagnosed with Dravet syndrome (likely pathogenic/pathogenic variants in SCN1A) and two with Genetic Epilepsy with Febrile Seizures Plus (SCN1B)." (PMID 35886038, 2022). "The epileptic encephalopathy Dravet syndrome is linked to heterozygous variants in SCN1A leading to haploinsufficiency in most patients, however, a subset of patients has SCN1B homozygous loss-of-function variants." (PMID 29740331, 2018). "In contrast, Scn1b−/− mouse somatosensory cortex is haploinsufficient for Scn1a, suggesting an additive mechanism for the severity of the null model via disrupted regulation of another Dravet syndrome gene." (PMID 38425576, 2023). "Moreover, SCN1B/β1 pathogenic variants have not been identified in typical Dravet syndrome patients." (PMID 37654020, 2024). "Human SCN1B mutations have been associated with generalized febrile seizures (GEFS+) and Dravet syndrome (DS)." (PMID 36541246, 2023). "In contrast, expression of two non-functional SCN1B alleles may result a more severe epileptic disease like the Dravet Syndrome." (PMID 26042039, 2015).
cardiac arrhythmia (14 papers, 2016 to 2025). Any disturbances of the normal rhythmic beating of the heart or MYOCARDIAL CONTRACTION. "VGSC β1/β1B-subunits are expressed in the nervous system and heart and variants of SCN1B, encoding the β1- and β1B-subunits, are associated with mild to severe forms of epilepsy and cardiac arrhythmias." (PMID 35394857, 2022). "SCN1B gene variants in humans have been implicated in inherited neurological disorders and cardiac arrhythmias, including Brugada, long QT, and sudden infant death syndromes." (PMID 35394857, 2022). "Consistent with evidence linking SCN1B variants to human cardiac disease, Scn1b-null mice also have cardiac arrhythmias that include bradycardia and prolonged Q-T intervals." (PMID 35603785, 2022). "Each of these gene groups has direct relationships to SCN1B-linked disease states, including epileptic encephalopathy, cardiac arrhythmia, and cancer." (PMID 33411695, 2021). "Noteworthy is that SCN1B genetic variants have also been associated with cardiac arrhythmias, including Brugada and long QT-interval syndromes." (PMID 33238377, 2020). "Mice null for Scn1b, which encodes NaV β1 and β1b subunits, have defects in neuronal development and excitability, spontaneous generalized seizures, cardiac arrhythmias, and early mortality." (PMID 33134290, 2020). "SCN1B variants, which are linked to epileptic encephalopathy and cardiac arrhythmia, may also be involved in cancer, especially through dysregulation of cell-cell or cell-matrix adhesion and transcriptional regulation." (PMID 33411695, 2021). "Loss-of-function (LOF) variants in SCN1B, encoding voltage-gated sodium channel β1 subunits, are linked to human diseases with high risk of sudden death, including developmental and epileptic encephalopathy and cardiac arrhythmia." (PMID 33411695, 2021). "Whether the change in Scn1b expression is causative of the increase in arrhythmia susceptibility observed in the LAPW warrants further consideration." (PMID 27149380, 2016). "Scn1b null mice have spontaneous generalized seizures, increased sensitivity to hyperthermia-induced seizures, ataxia, failure to thrive, cardiac arrhythmia, and SUDEP." (PMID 40923316, 2025). "Variants in the gene SCN1B, encoding the VGSC β1- and β1B-subunits, result in inherited neurological disorders and cardiac arrhythmias." (PMID 35394857, 2022). "A multidisciplinary evaluation of large sample sizes will help to recognize various seizures semiology, psychomotor retardation, co-existent cardiac arrythmias and risk of SUDEP in patients with SCN1B-associated early myoclonic encephalopathy." (PMID 36291443, 2022). "Furthermore, the L-type calcium channel (ICa–L) and some potassium channel (IKr and IKs) currents in iPSC-CMs from the patient were also reduced, which resulted probably from secondary changes induced by the SCN1B variants and could contribute to the occurrence of arrhythmias in BrS." (PMID 31737628, 2019). "Our data demonstrated that the hiPSC-CMs from a BrS-patient with SCN1B gene variants recapitulated the main features of BrS, showing reduced INa, APA and Vmax, an increased occurrence of arrhythmia-like events and enhanced sensitivity to ajmaline challenge." (PMID 31737628, 2019). "Moreover, the L-type calcium channel (ICa–L) and some potassium channel (IKr and IKs) currents in iPSC-CMs from the patient were also reduced, which resulted probably from secondary changes induced by the SCN1B variants and could contribute to the occurrence of arrhythmias in BrS." (PMID 31737628, 2019). "Here, we explored whether Scn1b also regulates cardiac atrial excitability to understand its potential role in the development of AF, the most common type of cardiac arrhythmia and a significant contributor to mortality." (PMID 35603785, 2022). "Multiple SCN1B and SCN3B mutations are associated with cardiac arrhythmia." (PMID 34867379, 2021).
cardiac arrhythmia (continued). "Because Scn1b-null mice also have altered CM excitability resulting in atrial and ventricular arrhythmias, we postulated that the high rate of SUDEP in DEE52 may involve cardiac arrhythmias in addition to severe seizures." (PMID 40763036, 2025).
atrial fibrillation (9 papers, 2019 to 2025). A disorder characterized by an electrocardiographic finding of a supraventricular arrhythmia characterized by the replacement of consistent P waves by rapid oscillations or fibrillatory waves that vary in size, shape and timing and are accompanied by an irregular ventricular response. "Additionally, variants in SCN1B have been also related to atrial fibrillation and cardiac conduction dysfunction." (PMID 31737628, 2019). "Scn1b-null hearts had a significant accumulation of atrial collagen, increased susceptibility to pacing induced atrial fibrillation (AF), sinoatrial node (SAN) dysfunction, and increased numbers of cholinergic neurons in ganglia that innervate the SAN." (PMID 35603785, 2022). "Some previous studies have established that genetic modification in sodium voltage-channel genes encoding for the cardiac β-subunits, such as SCN1B, SCN2B, SCN3B and SCN4B, can result in atrial fibrillation (AF)." (PMID 36362949, 2022).
Epileptic encephalopathy (9 papers, 2018 to 2025). A condition in which epileptiform abnormalities are believed to contribute to the progressive disturbance in cerebral function. "Variants in SCN1B, encoding β1, are associated with developmental and epileptic encephalopathy, early infantile developmental and epileptic encephalopathy, genetic epilepsy with febrile seizures plus, atrial fibrillation and Brugada syndrome." (PMID 35752364, 2022). "Early infantile developmental and epileptic encephalopathy resulting from homozygous SCN1B loss-of-function variants has a more severe clinical phenotype with earlier onset than typical DS." (PMID 35663268, 2022). "SCN1B variants are implicated in a variety of inherited pathologies, including epileptic encephalopathy and cardiac arrhythmias." (PMID 29740331, 2018). "Importantly, a review of the literature in light of our results suggests that early infantile DEE is a more appropriate terminology than either EIEE or DS for SCN1B‐linked epileptic encephalopathy." (PMID 31709768, 2019). "Scn1b null mice display early infantile developmental and epileptic encephalopathy and disrupted neuronal pathfinding and fasciculation, as well as altered cardiac excitability." (PMID 35752364, 2022). "Importantly, a review of the literature in light of our results suggests that the term, early infantile developmental and epileptic encephalopathy, is more appropriate than either EIEE or DS to describe biallelic SCN1B patients." (PMID 31709768, 2019).
developmental and epileptic encephalopathy (8 papers, 2019 to 2025). An epilepsy associated with developmental impairment that may be due to either the underlying etiology or the superimposed epileptic activity, or both. "Compared with classical DS, the clinical symptoms of patients with homozygous SCN1B mutations are more consistent with early infantile developmental and epileptic encephalopathy (DEE), and the latter is more severe than DS." (PMID 38174099, 2023). "Scn1b−/− mice, which model early infantile developmental and epileptic encephalopathy (OMIM 617350, DEE52) demonstrate the powerful influence of INa density variability on spiking correlation and neuronal synchronization." (PMID 37264112, 2023). "Individuals with monoallelic pathogenic variants in SCN1B often present with genetic epilepsy with febrile seizures plus (GEFS+), while those with biallelic pathogenic variants may present with developmental and epileptic encephalopathy (DEE)." (PMID 36291443, 2022).
Ventricular arrhythmia (8 papers, 2018 to 2025). "The SCN1b gene encodes for the Nav-β1 and -β1B subunits and is linked to atrial and ventricular arrhythmias." (PMID 41149262, 2025). "The defective Ca2+ cycling was normalized by inhibition of the tetrodotoxin-sensitive Na+ current and appeared to contribute to the enhanced susceptibility of Scn1b-null hearts to ventricular arrhythmias." (PMID 35394857, 2022). "Consistent with this, ventricular CMs isolated from cardiac-specific Scn1b null mice have increased INa density, increased susceptibility to polymorphic ventricular arrhythmias, and altered intracellular calcium handling that is TTX-S." (PMID 29740331, 2018). "In the human heart, SCN1B mRNA expression is 3 times higher in atria than in ventricles, suggesting that SCN1B variants may result in atrial as well as ventricular arrhythmias." (PMID 35603785, 2022). "Scn1b-null mice have spontaneous seizures and ventricular arrhythmias and die by approximately 21 days after birth." (PMID 35603785, 2022). "Scn1b deletion in mice results in severe seizures, ventricular arrhythmias, and sudden death prior to weaning." (PMID 29740331, 2018). "The NaV β-subunits play a critical role in the regulation of cardiac NaV channel function, as demonstrated in SCN1B- and SCN3B-null mice whose ventricular cardiomyocytes exhibit abnormal electrophysiology and propensity to ventricular arrhythmias." (PMID 34867379, 2021). "For ventricular arrhythmia, many of the significant proteins identified by the diffusion algorithm are ion channel proteins, such as those that contribute to Ca2+ (CACNA1C, CACNA1C-IT2), Na+ (SCN3A, SCN1B, SCN4B, SCN10A), or K+ (KCNQ1, KCNE3, KCNH2) transport in the heart." (PMID 39954672, 2025).
generalized epilepsy (6 papers, 2015 to 2025). Epilepsy that is characterized by generalized seizure types and may have typical interictal and/or ictal EEG findings that accompany generalized seizure types (for example generalized spike-wave). "In generalized epilepsy with febrile seizures plus (GEFS +) the presence of a gene SCN1B mutation (sodium channel voltage-dependent encoding gene, type I, β subunit) was reported, also described in the BrS." (PMID 37373791, 2023). "Genetic analysis identified a missense variant in the SCN1B gene (NM_199037.4: c.[363C > G]; [363C=] p.[Cys121Trp]; [Cys121=]), previously known to cause Febrile seizures and generalized epilepsy and classified to be likely pathogenic, according to the ACMG guidelines." (PMID 32466254, 2020). "For example, for SCN1B mutations related to CNS diseases, a single mutant allele may result in the development of a milder disease like generalized epilepsy with febrile seizures plus." (PMID 26042039, 2015). "For instance, the sodium channel 1 subgroup (SCN1B) is located on the 19th chromosome, while the 1 subgroup (SCN1A) resides on the 2nd chromosome; both have been identified as defective in cases of generalized epilepsy associated with febrile convulsions." (PMID 40647621, 2025).
developmental delay (5 papers, 2019 to 2025). "A 16-month-old male diagnosed with early infantile epileptic encephalopathy (DEE), Dravet-like syndrome and global developmental delay was found to have biallelic SCN1B genetic variants." (PMID 36291443, 2022). "While the observed prolonged febrile myoclonic or hemiclonic seizures were more concordant with DS, electroclinical evidence suggests that SCN1B‐linked DEE is more severe, with an earlier onset of seizures and developmental delay." (PMID 31709768, 2019).
Ataxia (4 papers, 2007 to 2025). Ataxia refers to impaired coordination of voluntary muscle movement. "We propose that proper Scn1b expression in the cerebellum is essential for motor control and that Scn1b deletion contributes to cerebellar ataxia and seizure severity." (PMID 40923316, 2025). "Scn1b null mice exhibit spontaneous seizures and ataxia, slowed action potential conduction, decreased numbers of nodes of Ranvier in myelinated axons, alterations in nodal architecture, and differences in Na+ channel α subunit localization." (PMID 17623064, 2007). "Interestingly, the null mouse model of Cntn1, encoding the IgSF-CAM contactin, which is a functional binding partner of VGSC β1 subunits, has a similar phenotype to Scn1b null mice, including death by P18, severe ataxia, and cerebellar micro-organization defects with aberrant CGN axon guidance." (PMID 40923316, 2025). "We showed previously that Scn1b-null mice model DEE52, with spontaneous generalized seizures, ataxia, and a 100% SUDEP rate." (PMID 40763036, 2025). "Three likely pathogenic variants in these genes were identified in Case-21 (CACNA1E p.Ile614Val), Case-25 (SCN1B p.Cys121Trp), and Case-31 (SCN9A p.Tyr1217Ter), with very late onset of ataxia at the age of 60, 59, and 56, respectively." (PMID 32466254, 2020).
febrile seizures (4 papers, 2011 to 2025). "Several pathogenic SCN1B genetic variants have been reported in individuals with DEEs including Dravet-like syndrome, genetic epilepsy with febrile seizures plus (GEFS+), and focal epilepsy." (PMID 36291443, 2022).
sudden infant death syndrome (4 papers, 2018 to 2022). Unexpected death in infancy which remains unexplained following autopsy, review of the medical history, and investigation of the death circumstances and death scene. "Inherited arrhythmia syndromes, including sudden infant death syndrome, have been linked with mutations in SCN1B, encoding the Na+ channel β1 subunit." (PMID 34206182, 2021). "Concerning the direct interaction of KV4.3 and NaV1.5, a mutation in the SCN1B gene encoding the cardiac sodium channel β1 subunit has been found in BrS and sudden infant death syndrome patients." (PMID 29593552, 2018).